RAB43 (RAB43, member RAS oncogene family)
Description:
The small GTPases Rab are key regulators of intracellular membrane trafficking, from the formation of transport vesicles to their fusion with membranes. Rabs cycle between an inactive GDP-bound form and an active GTP-bound form that is able to recruit to membranes different set of downstream effectors directly responsible for vesicle formation, movement, tethering and fusion. Involved in retrograde transport from the endocytic pathway to the Golgi apparatus. Required for the structural integrity of the Golgi complex. Also controls the anterograde ER-to-Golgi transport of nascent G protein-coupled receptors (including ADRA2A, ADRA2B, ADRA2C, ADRA1B, ADRB2 and AGTR1) and regulates the ER sorting of GPCR members by virtue of its ability to interact directly. Involved in the transport of Shiga toxin from early and recycling endosomes to the trans-Golgi network. Plays a role in the maturation of phagosomes that engulf pathogens, such as S.aureus and M.tuberculosis.
Synonyms: RAB41; RAB11B; ISY1
Tractability: Small molecule: a structure with a bound ligand is known. PROTAC: ubiquitination databases record sites on it; its protein half-life has been measured.
Gene: Protein-coding gene on chromosome 3 (129,087,569 to 129,123,694, reverse strand). Ensembl gene ENSG00000172780.
Subcellular location: Golgi apparatus; Golgi apparatus, cis-Golgi network membrane; Golgi apparatus, trans-Golgi network membrane; Endoplasmic reticulum membrane; Endoplasmic reticulum-Golgi intermediate compartment membrane; Cytoplasmic vesicle, phagosome membrane
Subcellular location (Human Protein Atlas): Plasma membrane
Pathways (Reactome):
Metabolism of proteins: RAB geranylgeranylation
Vesicle-mediated transport: Retrograde transport at the Trans-Golgi-Network
Gene Ontology:
Molecular function: G protein activity; GTPase activity; protein binding; GTP binding
Biological process: endoplasmic reticulum to Golgi vesicle-mediated transport; Golgi organization; phagosome maturation; regulation of Golgi organization; retrograde transport, plasma membrane to Golgi; virion assembly; autophagosome assembly
Cellular component: cis-Golgi network membrane; endoplasmic reticulum membrane; endoplasmic reticulum-Golgi intermediate compartment membrane; extracellular exosome; Golgi apparatus; Golgi membrane; phagocytic vesicle; trans-Golgi network membrane; phagocytic vesicle membrane
Genetic constraint (gnomAD): Loss-of-function variants: 6 observed, 16.27 expected, observed/expected ratio (o/e) 0.37, 90% interval 0.2 to 0.73. The upper end of that interval is the gene's LOEUF score, 0.73, which puts it in group 2 of 6, group 1 being the genes least tolerant of losing a copy. Missense variants: 152 observed, 209.56 expected, observed/expected ratio (o/e) 0.73, 90% interval 0.63 to 0.83. Synonymous variants: 82 observed, 87.94 expected, observed/expected ratio (o/e) 0.93, 90% interval 0.78 to 1.12.
Homologues: Orthologues: chimpanzee RAB43 (100% identical), dog RAB43 (94% identical), pig RAB43 (93% identical), guinea pig RAB43 (91% identical), mouse Rab43 (91% identical), tropical clawed frog rab43 (81% identical), zebrafish rab43 (71% identical). Paralogues in human: RAB19 (53% identical), RAB30 (50% identical), RAB11B (44% identical), RAB11A (44% identical), RAB4B (42% identical), RAB8B (42% identical), RAB10 (42% identical), RAB1B (41% identical), RAB2A (41% identical), RAB2B (41% identical), RAB4A (41% identical), RAB25 (41% identical), and 56 more.
Diseases named in the same sentence as RAB43 in open-access papers:
RAB43 is named in the same sentence as 15 diseases in open-access papers, as found by Europe PMC text mining. Sharing a sentence is not in itself a finding about the gene and the disease. The quoted sentences say what the papers report.
glioma (3 papers, 2019 to 2026). A benign or malignant brain and spinal cord tumor that arises from glial cells (astrocytes, oligodendrocytes, ependymal cells). "Rab43 has been implicated in glioma development previously, but the underlying mechanism is unclear." (PMID 31226964, 2019). "A study related to RAB43, another member of the RAB family, suggested that glioma patients with high RAB43 expression showed worse clinical outcomes when compared with low RAB43 expression glioma patients." (PMID 35741652, 2022).
chronic hepatitis C infection (1 paper, 2015). "• In the module of miR-34a and miR-214, besides the confirmed miR-214 and its mRNA RAB43, miR-34a has been reported to upregulate in both liver fibrosis and hepatocellular carcinoma, and serum levels of miR-34a are significantly higher in chronic hepatitis C infection patients than in controls." (PMID 25707620, 2015).
colon cancer (1 paper, 2019). "To further confirm the relevance of identified Rab43 variant to the onset of the studied familial cancer syndrome, we performed immunohistochemistry in colon tissues of the 54Y proband with colon cancer and in liver tissues of his farther died from liver cancer." (PMID 31226964, 2019).
hereditary cancer (1 paper, 2019). Malignant neoplasms occurring in families at a rate greater than that expected by chance and caused by germline mutations in a specific gene. "How a germline mutation on Rab43 gene is susceptible to hereditary cancer remains unclearly currently." (PMID 31226964, 2019).
liver cancer (1 paper, 2019). An epithelial or non-epithelial malignant neoplasm that arises from the liver. "While the patient’s healthy mother and two sisters are homozygous for wild type Rab43 alleles, the genome of his father who died from liver cancer indeed harbors one of the mutant allele of Rab43." (PMID 31226964, 2019). "Sanger DNA sequencing confirmed a mutation (c: 128810106C > T, p: A158T) occurred in one allele of Rab43 gene from the proband, that heterozygous mutation also was verified in the genome of the proband’s deceased father with liver cancer, but not in his healthy mother and sister." (PMID 31226964, 2019). "We found high levels of Rab43 protein occurred in both colon and liver cancer tissues, whereas much less of Rab43 was detected in their adjacent non-cancerous tissues." (PMID 31226964, 2019).
neuroblastoma (1 paper, 2021). Neuroblastoma (NB) is the most common solid, extracranial childhood tumor. "We next compared the effects of Rab43 on the surface transport of α2-AR and mAChR in human-derived neuroblastoma SHSY5Y cells and rat renal tubular epithelial NRK49F cells." (PMID 33676895, 2021).
Parkinson's (1 paper, 2021). "We exploit this assay to demonstrate that in Parkinson's patients with VPS35[D620N] mutations, phosphorylation of multiple Rab proteins (Rab1, Rab3, Rab8, Rab10 and Rab43) is elevated." (PMID 33367571, 2021).
cancer (2 papers, 2019 to 2025). A tumor composed of atypical neoplastic, often pleomorphic cells that invade other tissues. "We screened an array of human cancer cell lines and found the expression levels of Rab43 are varied dramatically." (PMID 31226964, 2019). "Finally, a positive correlation between the expression levels of Rab43 protein and cancer development in that family was confirmed." (PMID 31226964, 2019). "Given the fact that the proband and his father were heterozygous carriers of the Rab43 mutant allele, we are not sure whether the high levels of Rab43 observed in cancer tissues is contributed by elevated expression of Rab43 A158T alone." (PMID 31226964, 2019). "Eventually, a total of 15 cancerous or non-cancerous tissue sections from the proband or his father were analyzed, the overall expression difference of Rab43 protein in between cancer tissues and non-cancerous tissues is statistically significant (p < 0.001)." (PMID 31226964, 2019).
neurological diseases (1 paper, 2021). "As such, further studies are needed to define the functional roles of Rab43-mediated GPCR trafficking and sorting in the pathology of neurological diseases." (PMID 33676895, 2021).
RAB43 also shares sentences with these, for which no sentence is quoted: infection (2 papers); breast carcinoma (1); hepatocellular carcinoma (1); hereditary cancer syndrome (1); liver fibrosis (1); tumor (1).